CYP1B1 (cytochrome P450 family 1 subfamily B member 1)
Diseases named in the same sentence as CYP1B1 in open-access papers (continued):
Sharing a sentence is not in itself a finding about the gene and the disease.
diabetes (6 papers, 2021 to 2025). "As type 2 diabetes mellitus is a common comorbidity in patients, these observations further support the notion that targeting CYP1B1 has therapeutic potential in COPD." (PMID 40971194, 2025). "The present review aims at providing significant insight into the physiological and pathological role of AhR and its regulated enzymes, such as cytochrome P450 1A1 (CYP1A1) and CYP1B1 in both types of diabetes." (PMID 36418969, 2022). "Of the top 15 proteins found by Cytoscape 3.6.1, 8, CAT and OGG1 (downregulated) and CASP3, COMT, CYP1B1, DPYD, NQO1, and PTGS1 (upregulated), were dysregulated in diabetes-related kidney disease." (PMID 34367469, 2021).
glioma (6 papers, 2015 to 2024). A benign or malignant brain and spinal cord tumor that arises from glial cells (astrocytes, oligodendrocytes, ependymal cells). "It is worth mentioning that the presence of CYP1B1 has been solely detected in medulloblastoma, distinguishing it from other types of central nervous system tumors." (PMID 38214842, 2024). "Using immunohistochemical analysis, it was recently demonstrated that CYP1B1 is expressed in gliomas and the level of expression depends on tumor type and grade." (PMID 26580399, 2015). "Also, the CYP1B1 gene is a target of the miR-27b which is up-regulated in gliomas samples and glioma cells compared with low grade astrocytoma cells." (PMID 26580399, 2015). "The authors analyzed by microarray the transcriptome of kynurenine-treated glioma and found an AHR signature, characterized by an upregulation of AHR-target genes such as CYP1B1 (Cytochrome P450 family 1 subfamily B member 1) and TIPARP (TCDD-inducible poly-ADP-ribose polymerase)." (PMID 36188218, 2022).
non-small cell lung carcinoma (6 papers, 2018 to 2025). A group of at least three distinct histological types of lung cancer, including non-small cell squamous cell carcinoma, adenocarcinoma, and large cell carcinoma. "Previous studies have reported that microRNA-187-5p attenuates cancer cell progression in non-small cell lung cancer through the transcriptional repression of CYP1B1." (PMID 38612589, 2024). "Besides that, carriers of CYP1B1 4326 GG genotype was also associated with shorter PFS and overall survival (OS) in non-small-cell lung carcinoma (NSCLC) patients treated with docetaxel as compared to carriers of CYP1B1 4326 CC and CG genotypes." (PMID 33906328, 2021). "Moreover, CYP1B1 silencing is significantly reduced cisplatin resistance in cisplatin-resistant non-small cell lung cancer cells." (PMID 34680513, 2021).
pancreatic cancer (6 papers, 2008 to 2024). "Incidentally, CYP2W1 is important for the activation and response to chemotherapy, such as mitotane in cancer, whereas high expression of CYP1B1 is known to drive gemcitabine resistance in pancreatic cancer." (PMID 39000545, 2024). "Thus, it would be of interest to examine the expression and function of CYP1B1 in pancreatic cancer and determine its relationship with CASP1." (PMID 28388569, 2017).
Hepatic steatosis (5 papers, 2019 to 2026). Steatosis is a term used to denote lipid accumulation within hepatocytes. "Studies have shown that hepatic steatosis and tumorigenesis could be reduced by inhibiting CYP1B1." (PMID 31467589, 2019).
lung adenocarcinoma (5 papers, 2009 to 2021). A carcinoma that arises from the lung and is characterized by the presence of malignant glandular epithelial cells. "In the absence of exogenous ligands, AhR overexpression upregulated the expression of CYP1B1 in the early stage of lung adenocarcinoma." (PMID 25068070, 2013). "Increased expression of CYP1B1 by cigarette smoke was shown in vivo in buccal cells after smoke stimulation, in bronchial airway epithelial cells from smokers and in vitro in A549 lung adenocarcinoma cells." (PMID 31331382, 2019). "In a patient cohort of 204 lung adenocarcinoma patients, STAT3 and CYP1B1 expression correlated with IDO1 expression." (PMID 24657910, 2014).
lymph node metastasis (5 papers, 2013 to 2025). "In our study, significant associations were determined between CYP1B1 expression and tumor grade, lymph node metastasis, and HPV 16/18 expression." (PMID 34636736, 2021). "Moreover, overexpression of CYP1B1 is associated with larger tumor sizes, recurrent lymph node metastasis, advanced tumor grades, and lymphovascular invasion." (PMID 34636736, 2021). "Additionally, CYP1B1 expression was also associated with TNM staging (p < 0.05) and its expression was increased in patients with lymph node metastasis." (PMID 33692504, 2021). "Moreover, CYP1B1 expression was found to be high in all patients with lymph node metastasis." (PMID 34636736, 2021).
lymphoma (5 papers, 2004 to 2025). A malignant (clonal) proliferation of B- lymphocytes or T- lymphocytes which involves the lymph nodes, bone marrow and/or extranodal sites. "As Bcl-2 was reported a FOXO10 target in lymphoma, we test whether CYP1B1 can affect the expression of Bcl-2 in CRC cells." (PMID 37059712, 2023). "Notably, since CYP1B1 catalyzes the activation of 7,12‐Di‐Methyl‐Benz[a] Anthracene (DMBA), Cyp1b1‐null mice have a drastic decreased frequency to develop malignant lymphomas after administration with DMBA compared to wild‐type mice." (PMID 39806854, 2025). "In addition, the expression of AhR, CYP1A1, CYP1B1, RUNX1 and SLC7A8 was upregulated in MEPs of individuals with lymphoma, concomitant with enhanced nuclear localization of AhR." (PMID 37919525, 2023). "Important roles of Cyp1b1 in PAH carcinogenesis have been proposed by Gonzalez and co-workers who observed that Cyp1b1 knock-out mice expressing significant levels of Cyp1a1 are highly resistant to lymphoma formation by 7,12-DMBA." (PMID 15315710, 2004).
renal dysfunction (5 papers, 2019 to 2025). "Conversely, CYP1B1 inhibition has been shown to lower blood pressure and mitigate endothelial and renal dysfunction, as well as fibrosis, while simultaneously reducing ROS production." (PMID 41487507, 2025).
squamous cell carcinoma (5 papers, 2009 to 2022). A carcinoma arising from squamous epithelial cells. "CYP1B1 expression was detected in 91% (86/95) of the squamous cell carcinomas and all cases of adenocarcinomas and endometrioid adenocarcinomas." (PMID 34636736, 2021). "In squamous cell carcinoma of the head and neck, CYP1B1 knockdown reduced the migration and proliferation of premalignant cells and CYP1B1-mediated estrogen metabolism is essential for cancer development." (PMID 28388569, 2017). "In addition, CYP1B1 and CYP2A6 polymorphisms were inversely associated with adenocarcinoma and squamous cell carcinoma risk, respectively." (PMID 19479063, 2009).
type 2 diabetes (5 papers, 2016 to 2025). "Six out of twenty selected genes with largest expression difference (CYP1B1, GPT), genes linked to PCOS (RAB5B) or type 2 diabetes (PPARG, SVEP1), and methylation (DMAP1) were replicated in a separate case-control study." (PMID 26975253, 2016).
colitis (4 papers, 2013 to 2025). Inflammation of the colon. "A recent study indicated that the aromatic compounds in coffee could promote the expression of CYP1A1 and CYP1B1 by activating AhR, which alleviates experimental colitis." (PMID 36145261, 2022). "In addition, western blotting results revealed multiple functions of RSBDP in the DSS-induced colitis which were exerted by anti-inflammatory and pro-apoptotic activities, relying on the AhR/CYP1B1 and AKR1C1/PI3K/AKT pathways." (PMID 36145261, 2022). "Furthermore, administration of myricet in significantly increased the relative expressions of CYP1A1 and CYP1B1, whereas AhR inhibitor abolished the amelioration of myricetin on DSS-induced colitis." (PMID 39974840, 2025). "It is possible that the accumulation of AhR ligands in Cyp1a1-/- mice may not be at the same levels compared to triple Cyp knockout mice (lack of CYP1A1, CYP1A2 and CYP1B1 enzymes) to render the beneficial activities against DSS-induced colitis." (PMID 36159798, 2022).
coloboma (4 papers, 2017 to 2022). An abnormality in which a part of a structure in one or both eyes is missing. "At 96 hpf, cyp1b1 overexpression inhibited Mk cartilage development and caused eye wall defects and colobomas (1E', arrows)." (PMID 28192799, 2017). "Similar to the effects observed with the zebrafish gene, the overexpression of human CYP1B1 caused large colobomas in 71.8 ± 17.9% of embryos (P = 0.0003), reflecting the defective closure of the ocular fissure (8B') compared to controls (8A')." (PMID 28192799, 2017). "Indeed, the overexpression of Cyp1b1 prevents fissure closure, resulting in colobomas in zebrafish, and a handful of case reports of superior coloboma have been associated with Cyp1b1 gene mutations." (PMID 33425902, 2020). "In addition, targeted manipulations of orthologues of both CHRDL1 and CYP1B1 have recently been shown to cause coloboma phenotypes in Xenopus and zebrafish, respectively." (PMID 31162046, 2019). "Cyp1b1 regulated the expression of vsx2, pax6, and shh, genes clinically associated with colobomas." (PMID 28192799, 2017). "However, whether this variant is a gain-of-function mutation remains unknown, indicating that additional studies are required to further identify and assess mutations in human CYP1B1 in cases of colobomas." (PMID 28192799, 2017). "In the present study, we demonstrated that cyp1b1 is expressed in the dorsal and ventral retina and retinal pigment epithelium, specifically in the ocular fissures, and maintains fissure patency, such that decreased expression caused premature closure, while overexpression resulted in colobomas." (PMID 28192799, 2017). "Importantly, administration of human CYP1B1 mRNA to embryos resulted in large colobomas in 71.8 ± 17.9% of embryos and disrupted NC-derived tissue formation, supporting evolutionary conservation of cyp1b1 function between zebrafish and humans." (PMID 35663518, 2022). "Because Cyp1b1 regulation of ocular fissure closure was not mediated through RA, genes clinically associated with colobomas were investigated as downstream targets." (PMID 28192799, 2017). "Interestingly, overexpression of cyp1b1 resulted in large colobomas." (PMID 28192799, 2017). "These included the known human coloboma associated genes (indicated by #): SMOC1, PAX2, VAX1 and ALDH6, in addition to the coloboma candidates from other animal studies CHRDL1 and CYP1B1 (indicated by •)." (PMID 31162046, 2019). "The ATG MO-mediated knockdown of endogenous zebrafish Cyp1b1 showed improvement of craniofacial defects, but did not statistically significantly decrease the percentage of embryos with colobomas and craniofacial defects (36.4 ± 17.0, P = 0.06) due to human CYP1B1 overexpression (8C')." (PMID 28192799, 2017).
head and neck squamous cell carcinoma (4 papers, 2011 to 2025). A squamous cell carcinoma that arises from any of the following anatomic sites: lip and oral cavity, nasal cavity, paranasal sinuses, pharynx, larynx, and salivary glands. "In head and neck squamous cell carcinoma (HNSCC) models, CYP1B1 was among the most abundant enzyme in SCC9 cells." (PMID 41174467, 2025).
liver fibrosis (4 papers, 2019 to 2025). "We also measured hepatic expression of genes involved in detoxification/drug metabolism (Cyp1a1, Cyp1b1), inflammation (Il1b) and hepatic fibrosis (Col1a1)." (PMID 35788891, 2022). "Furthermore, the expression of the CYP1B1 in CCl4-induced hepatic fibrosis rats was significantly inhibited after AR treatment (P < 0.01)." (PMID 31467589, 2019). "Taken together, our study found that AR could be involved in the regulation of arachidonic acid metabolism and ether lipid metabolism by regulating the expression of CYP1A2, PCYT1A and CYP1B1, thereby effectively improving liver fibrosis." (PMID 31467589, 2019). "Cyp1b1 substantially affects hepatic vascular and stellate cells (HSC) with linkage to liver fibrosis." (PMID 40076634, 2025). "The role of HSCs in liver fibrosis and NAFLD depends on their Cyp1b1 activity." (PMID 40076634, 2025). "The results of RT-PCR in liver tissue of rats with liver fibrosis showed that the expression of CYP1A2 and PCYT1A was up-regulated and the expression of CYP1B1 was down-regulated in AR treatment groups, which was consistent with the previously reported results." (PMID 31467589, 2019). "Metabolomics combined with network pharmacology was used for the first time to clarify that the treatment of AR on liver fibrosis, which is related to the regulation of arachidonic acid metabolism and ether lipid metabolism by modulating the expression of CYP1A2, CYP1B1 and PCYT1A." (PMID 31467589, 2019).
oral cancer (4 papers, 2011 to 2020). "The MiRNA target prediction showed functional molecular annotation including specific miRNA-targets hsa-miR-4282, hsa-miR-2052, hsa-miR-216a-3p, for CYP1B1, C7, and ADCY2 respectively associated with oral cancer." (PMID 32887903, 2020). "The fact that CYP1B1 expression is higher in the normal tissues might aid to the development of chemopreventive drugs for oral cancer." (PMID 22114726, 2011). "Cigarette smoke has been shown to induce cytochrome P450 (CYP1A1, CYP1B1) and aldo-keto reductase (AKR1C1, AKR1C3, AKR1B10) genes in oral dysplasia and primary oral carcinoma cell lines." (PMID 28467356, 2017).
oral squamous cell carcinoma (4 papers, 2011 to 2023). "Overexpression of common genes associated with tobacco-induced oral squamous cell carcinoma (OSCC), such as MMP1, MMP3, MMP9, YAP1, CYP1A1, and CYP1B1, was also observed." (PMID 36835505, 2023). "It was reported that methoxylated flavonoids have the ability to inhibit CYP1B1 activity and mRNA expression in human oral squamous cell carcinoma SCC-9 cells." (PMID 35662936, 2022).
osteoarthritis (4 papers, 2019 to 2025). A noninflammatory degenerative joint disease occurring chiefly in older persons, characterized by degeneration of the articular cartilage, hypertrophy of bone at the margins and changes in the synovial membrane. "During osteoarthritis progression m6A might act at upstream of estrogen signal by regulating CYP1B1, a major enzyme in estrogen metabolism." (PMID 40180675, 2025). "By validation of DEGs of GSE55457, three common proteins, PIM1, CYP1B1, and HSPA2, were considered as the key targeted proteins of the quercetin during the treatment of osteoarthritis by Achyranthes bidentata." (PMID 31998395, 2019). "In conclusion, the docking of PIM1-quercetin, CYP1B1-quercetin, and HSPA2-quercetin may play important roles during the treatment of osteoarthritis by Achyranthes bidentata." (PMID 31998395, 2019). "The docking of PIM1-quercetin, CYP1B1-quercetin, and HSPA2-quercetin may play important roles during the treatment of osteoarthritis by Achyranthes bidentata." (PMID 31998395, 2019).
prostate tumors (4 papers, 2016 to 2024). "CYP1B1 was significantly (p < 0.05) overexpressed specifically in prostate tumors from poor responders versus good responders or compared to normal cells." (PMID 38534761, 2024). "Elevated CYP1B1 expression in prostate tumors and particularly in poor responders underscores a high potential for drug resistance." (PMID 38534761, 2024). "There was a significant (p < 0.05) upregulation of CYP1B1 in prostate tumors compared to normal prostate tissues." (PMID 38534761, 2024). "The expression of CYP1B1 was significantly higher in tumor tissues than in normal tissues, such as breast, ovarian and prostate tumors, and CYP1B1 functions as an oncogene that promotes tumor progression in multiple tumors." (PMID 36085146, 2022). "Decreased prostate tumor growth was observed in tumors expressing CYP1B1 shRNA #4-2 compared to those expressing control shRNA." (PMID 28388569, 2017). "CYP1B1 expression has been found in both normal prostate tissues and prostate tumors including normal-adjacent tissues, with markedly higher levels in PCa compared with benign tissues." (PMID 28388569, 2017). "These evidences strongly suggest that CYP1B1 plays a potentially crucial role in prostate tumor development and progression." (PMID 28388569, 2017). "CYP1B1 expression has been reported to be higher in tumors compared to normal tissues, especially in hormone-related cancers including breast, ovary, and prostate tumors." (PMID 26981862, 2016). "The antitumor effect of CYP1B1 shRNA was also observed in prostate tumor xenograft mouse models." (PMID 28388569, 2017). "Prostate tumors with strong CYP1B1 expression showed low CASP1 levels." (PMID 28388569, 2017). "However, its expression is elevated in tumors compared to normal tissues, especially in hormone-related cancers including breast, ovary, and prostate tumors and the pre-disposing potential of CYP1B1 for various cancers also has been widely reported." (PMID 26981862, 2016). "Although high expression of CYP1B1 has been demonstrated in prostate tumors, there are no reports regarding the correlation of its expression with clinicopathologic characteristics." (PMID 28388569, 2017).
pulmonary hypertension (4 papers, 2016 to 2023). Increased pressure within the pulmonary circulation due to lung or heart disorder. "The results do suggest, however, a close relationship between adipose tissue CYP1B1 expression, the development of pulmonary hypertension and effectiveness of ANA in normoxic ob/ob male mice." (PMID 30923189, 2019). "Given the significant increase in CYP1B1 and its product 16αOHE1 in obese male mice we assessed the effect of TMS, a selective CYP1B1 inhibitor, on the pulmonary hypertension phenotype observed in male ob/ob mice." (PMID 30923189, 2019). "The relationships between the development of pulmonary hypertension, CYP1B1 and effectiveness of ANA are, however, less clear in hypoxic male mice." (PMID 30923189, 2019). "CYP1B1 is highly upregulated within pulmonary arterial lesions of PAH patients and pharmacological inhibition of CYP1B1 can attenuate the development of experimental pulmonary hypertension." (PMID 30923189, 2019).
acute myeloid leukemia (3 papers, 2023 to 2024). Acute myeloid leukemia (AML) is a group of neoplasms arising from precursor cells committed to the myeloid cell-line differentiation. "UCA1 stabilizes METTL14 allowing the writer to deposit m6A marks on target mRNAs, such as CYP1B1 and CXCR4, leading to acute myeloid leukemia (AML) development." (PMID 39280246, 2024). "LncRNA UCA1 promotes acute myeloid leukemia (AML) progression by affecting the stability of METTL14 and upregulating the expression of CXCR4 and cytochrome P450 family 1 subfamily B member 1 (CYP1B1)." (PMID 38351139, 2024).
allergic disease (3 papers, 2022 to 2023). An immune response that occurs following re-exposure to an innocuous antigen, and that requires the presence of existing antibodies against that antigen. "The European-specific CYP1B1 missense variant of rs1800440 (N453S) was associated with allergic diseases susceptibility." (PMID 35753705, 2022). "Our study newly identified six loci associated with allergic diseases (MIIP, CXCR4, SCML4, CYP1B1, ICOS and LINC00824) and four pleiotropic loci associated with both autoimmune and allergic diseases (PRDM2, G3BP1, HBS1L and POU2AF1)." (PMID 35753705, 2022). "Following HDM-induced allergy, ECs from AhR-/- showed a strongly altered gene expression profile, contrarily to CYP1B1-/-, which showed only low DEGs compared to WT with and none without allergy." (PMID 35734174, 2022).
Blindness (3 papers, 2017 to 2023). Blindness is the condition of lacking visual perception defined as a profound reduction in visual perception. "PCG, due to its CYP1B1 gene variants, is an important cause of blindness in many populations." (PMID 36833236, 2023).
clear cell renal cell carcinoma (3 papers, 2004 to 2025). "EROD activity was identified in 82% of clear-cell renal carcinomas (n=19/23) (65–992 fmol min mg−1 of microsomal protein) with similar levels of CYP1B1 activity also demonstrated in the chromophobe (n=2) and papillary renal carcinomas (n=1)." (PMID 15280921, 2004).